DDX10 (DEAD-box helicase 10)
Description:
Putative ATP-dependent RNA helicase that plays various role in innate immunity or inflammation. Plays a role in the enhancement of AIM2-induced inflammasome activation by interacting with AIM2 and stabilizing its protein level. Negatively regulates viral infection by promoting interferon beta production and interferon stimulated genes/ISGs expression.
Synonyms: HRH-J8; Dbp4
Tractability: Small molecule: a structure with a bound ligand is known. PROTAC: UniProt records ubiquitination sites on it; ubiquitination databases record sites on it; its protein half-life has been measured.
Target class: Enzyme; Hydrolase
Gene: Protein-coding gene on chromosome 11 (108,665,053 to 108,940,999, forward strand). Ensembl gene ENSG00000178105.
Subcellular location: Cytoplasm; Nucleus; Nucleus, nucleolus
Subcellular location (Human Protein Atlas): Nucleoli
Gene Ontology:
Molecular function: protein binding; RNA binding; RNA helicase activity; ATP binding; ATP hydrolysis activity; nucleic acid binding
Biological process: rRNA processing
Cellular component: cytoplasm; nucleus; nucleolus
Genetic constraint (gnomAD): Loss-of-function variants: 62 observed, 89.08 expected, observed/expected ratio (o/e) 0.7, 90% interval 0.57 to 0.86. The upper end of that interval is the gene's LOEUF score, 0.86, which puts it in group 3 of 6, group 1 being the genes least tolerant of losing a copy. Missense variants: 861 observed, 976.73 expected, observed/expected ratio (o/e) 0.88, 90% interval 0.83 to 0.93. Synonymous variants: 315 observed, 337.94 expected, observed/expected ratio (o/e) 0.93, 90% interval 0.85 to 1.02.
Cancer hallmarks: suppression of growth (promotes)
Homologues: Orthologues: chimpanzee DDX10 (99% identical), macaque DDX10 (92% identical), rabbit DDX10 (90% identical), dog DDX10 (89% identical), rat Ddx10 (86% identical), mouse Ddx10 (85% identical), guinea pig DDX10 (84% identical), tropical clawed frog ddx10 (63% identical), zebrafish ddx10 (59% identical), Drosophila melanogaster CG5800 (40% identical), Caenorhabditis elegans ddx-10 (36% identical). Paralogues in human: DDX18 (27% identical), DDX31 (22% identical), DDX55 (19% identical), DDX27 (18% identical), DDX21 (17% identical), DDX42 (17% identical), DDX54 (17% identical), DDX47 (17% identical), DDX50 (17% identical), DDX24 (16% identical), DDX17 (15% identical), DDX46 (15% identical), and 26 more.
Diseases named in the same sentence as DDX10 in open-access papers:
DDX10 is named in the same sentence as 29 diseases in open-access papers, as found by Europe PMC text mining. Sharing a sentence is not in itself a finding about the gene and the disease. The quoted sentences say what the papers report.
breast carcinoma (6 papers, 2008 to 2022). "Through gene rearrangement studies, Dr. Jiao confirmed that DDX10 is a potential oncogene affecting the growth and proliferation of breast cancer cells." (PMID 35109823, 2022). "Several interactors in this group were also identified as substrates, including the RNA helicase DDX10, the guanine nucleotide binding protein GNL1 and RRP1B, a ribosomal RNA processing protein which has been linked as a susceptibility marker in breast cancer." (PMID 29214152, 2017). "DDX10 promotes the proliferation of breast cancer, osteosarcoma and ovarian cancer cells." (PMID 35109823, 2022). "Moreover, downregulation of DDX10 in breast cancer cells lead to an increased frequency of apoptotic nuclear morphology." (PMID 23496902, 2013). "RNA interference-mediated suppression of five candidate genes (DDX10, SKA3, EPHA5, CLTC and TNIK) led to inhibition of breast cancer cell growth." (PMID 23496902, 2013). "For DDX10 there is one paper which co-cites DDX10 and one of its 11 predicted targets, TNFSF14, in a study of changes in hormone receptor target genes and chromatin modifying enzymes after proteasome inhibition in breast cancer cells." (PMID 25148247, 2014). "Using whole genome mate pair sequencing and RNA interference assays, we have discovered a number of novel gene rearrangements in breast cancer genomes and identified DDX10, SKA3, EPHA5, CLTC and TNIK as potential cancer genes with impact on the growth and proliferation of breast cancer cells." (PMID 23496902, 2013).
osteosarcoma (6 papers, 2020 to 2023). A usually aggressive malignant bone-forming mesenchymal neoplasm, predominantly affecting adolescents and young adults. "High expression of CYP26B1, GP1BB, and IFI44 in osteosarcoma patients was correlated with good prognosis, while high expression of DDX10 and FOXA2 in osteosarcoma patients was associated with poor prognosis." (PMID 32284759, 2020). "DDX10, the second altered gene, in this case, is a known cancer-related gene, and its somatic overexpression has been recently reported to be associated with a lower survival rate in osteosarcoma patients." (PMID 32371905, 2020). "Among them, MLLT3, ATM/ATR, DDX10, CASP1 and BRD4 have been extensively studied and shown to be associated with pathogenesis or clinical outcomes in osteosarcoma." (PMID 37894336, 2023). "DDX10 is an RNA helicase that is frequently lost in ovarian cancer and is a poor prognostic factor in osteosarcoma." (PMID 35269844, 2022). "Recently, it was confirmed that the expression of DDX10 is significantly higher in osteosarcoma patients." (PMID 35109823, 2022). "DDX10 is significantly overexpressed in osteosarcoma cancer patients." (PMID 33657088, 2021). "Our second representative case was a female patient with osteosarcoma, diagnosed at 10, who carried a pathogenic variant in GJB2 in addition to a germline duplication of DDX10, the latter, a known marker somatically associated with poor prognosis for osteosarcoma." (PMID 32371905, 2020). "Three of highly expressed genes (DDX10, FOXA2, and HEY1) were correlated with poor prognosis, while three of lowly expressed genes (CYP26B1, GP1BB, and IFI44) showed the opposite trend in patients with osteosarcoma." (PMID 32284759, 2020).
colorectal cancer (3 papers, 2022 to 2023). A primary or metastatic malignant neoplasm that affects the colon or rectum. "A Expression of DDX10 in several colorectal cancer cell lines by q-PCR; MTT cell proliferation assay was applied." (PMID 35109823, 2022). "Previous studies proved that DDX10 could promote proliferation or metastasis of tumor cells in lung cancer, colorectal cancer, and ovarian cancer." (PMID 36506302, 2022).
ovarian carcinoma (3 papers, 2022). A malignant neoplasm originating from the surface ovarian epithelium. "Studies have shown that decreased expression of DDX10 promotes the proliferation of ovarian cancer through the Akt/NF-kB pathway." (PMID 35109823, 2022). "Interestingly, DDX10 plays an antitumour role in the development of ovarian cancer." (PMID 35109823, 2022).
gastric cancer (2 papers, 2024 to 2025). A primary or metastatic malignant neoplasm involving the stomach. "The distribution of mutations of 133 UPR related genes in stomach cancer were exhibited in waterfall plot, it is estimated that EIF4G1, DDX10, and EIF2AK3, which have the highest mutation rate, have a mutation rate of 4%, and the mutation type is predominantly missense mutations." (PMID 38700505, 2024). "However, survival analysis revealed that GABRD and DDX10 did not exhibit significant differences in gastric cancer prognosis." (PMID 40444099, 2025).
leukaemia (2 papers, 2013 to 2022). "Previous studies have shown that the fusion of NUP98 and DDX10 may lead to leukaemia." (PMID 35109823, 2022).
melanoma (2 papers, 2022). A malignant, usually aggressive tumor composed of atypical, neoplastic melanocytes. "Evaluation of the predictive power of this novel signature in silico on an ICI-treated melanoma patient cohort extracted from GEO and EGA databases, revealed WFDC1, EFNA3, DDX10, and PTBP1 as marker genes." (PMID 35269844, 2022). "Since DDX10 is a strong enhancer of α-synuclein-induced toxicity, we can employ SDL interaction between DDX10 and α-synuclein and use α-synuclein inhibitors as promising therapeutics for cancer, such as melanoma." (PMID 36761420, 2022).
acute myeloid leukemia (1 paper, 2026). Acute myeloid leukemia (AML) is a group of neoplasms arising from precursor cells committed to the myeloid cell-line differentiation. "Moreover, DDX10 participates in oncogenic fusion events, most notably the NUP98::DDX10 fusion identified in a subset of acute myeloid leukemias, which drives leukemogenesis by disrupting transcriptional regulation and cellular differentiation." (PMID 41751522, 2026).
colon adenocarcinoma (1 paper, 2023). "Interestingly, there was a strong correlation between DDX10 expression and the number of infiltrating immune cells, including CD4+ T cells, CD8+ T cells and macrophages, in colon adenocarcinoma (COAD), which was analyzed by the TIMER database." (PMID 38023215, 2023).
myelodysplastic syndrome (1 paper, 2012). A clonal hematopoietic disorder characterized by dysplasia and ineffective hematopoiesis in one or more of the hematopoietic cell lines. "One of these is DDX10 which, like Psip1/Ledgf, is found as a fusion partner with Nup98 in myeloid leukaemias and myelodysplastic syndromes, perhaps indicative of their function in a common pathway that is mis-regulated in these malignancies." (PMID 22615581, 2012).
Obesity (1 paper, 2022). Accumulation of substantial excess body fat. "UTP14A, DKC1, DDX10, PinX1, and ESF1 have been identified as hub genes in obesity-induced pathological changes in the heart and may be involved in obesity-induced cardiac injury by affecting cardiac microcirculatory function." (PMID 35734237, 2022). "UTP14A, DKC1, DDX10, PinX1, and ESF1 may be involved in obesity-induced cardiac injury by affecting angiogenesis in the heart." (PMID 35734237, 2022).
viral infection (1 paper, 2023). "The N protein of SARS-CoV-2 has been found to interact with several RNA helicases, including DDX1, DDX3, DDX5, DDX6, DDX21, and DDX10; among them, DDX1, DDX5, and DDX6 are essential for virus replication, while DDX21 and DDX10 restrict the viral infection." (PMID 38328580, 2023).
cancer (15 papers, 2013 to 2026). A tumor composed of atypical neoplastic, often pleomorphic cells that invade other tissues. "The tumor suppressor gene DDX10 has been associated with inhibition of tumor growth, and its reduced expression has been implicated in accelerated cancer progression." (PMID 40486961, 2025). "DEAD/H box RNA helicase 10 (DDX10) is associated with a variety of cancers and diseases of the blood system." (PMID 35734237, 2022). "An elevated level of DDX10 is linked to diseases such as cancer or neurodegeneration." (PMID 33657088, 2021). "Aberrant DDX10 expression is a recurrent feature across multiple cancers, where it promotes tumor progression, therapy resistance, and poor prognosis." (PMID 41751522, 2026). "By consolidating current knowledge under this unifying framework, this review highlights the multifaceted roles of DDX10 in cancer biology, advocating further research into its molecular functions and translational potential." (PMID 41751522, 2026). "We analysed the gene expression of 50 paired cancer and paracarcinoma tissues selected from the TCGA database and found that the mRNA expression of DDX10 in CRC tissues was evidently higher than that in paracarcinoma tissues." (PMID 35109823, 2022). "Our pancancer analysis results showed that DDX10 is highly expressed in a variety of cancer tissues; therefore, DDX10 is likely to be a key gene in many cancers." (PMID 35109823, 2022). "DDX10 is an ATP-dependent RNA helicase, but, to our knowledge, little is known about its phosphorylation and function in cancer." (PMID 31675377, 2019). "An elevated expression of DDX10 in cancer leads to a poor survival rate in chondrosarcoma patients." (PMID 36761420, 2022). "However, this may be context dependent as DDX10 is found to be both overexpressed as well as lost in cancers." (PMID 36761420, 2022). "Notably, two proteins are associated with phosphosites significantly deregulated in all three PC cell lines as compared to PNT1A: TP53BP1, well-known cancer-related phosphosites downregulated in all three PC cell lines and DDX10, a potential new candidate, upregulated in PCa cell lines." (PMID 31675377, 2019). "DEAD-box ATPase 10 (DDX10), a prominent RNA-binding protein in the DDX family, has a critical function in cancer progression." (PMID 40352946, 2025).
tumor (10 papers, 2013 to 2026). "Given its tumor-associated expression and diverse biological functions, DDX10 is increasingly recognized as a potential diagnostic biomarker and a promising target for therapeutic strategies." (PMID 41751522, 2026). "Translocations in FOXO3/PDGFD and DDX10/SKA3 are interesting due to their possible role in tumor cell growth and survival." (PMID 36831263, 2023). "In our study, the data from multiple databases were used to verify that the expression of DDX10 in tumour tissues was evidently higher than that in normal tissues, and the difference was also obvious in tumour-node-metastasis (TNM) stage and Dukes’ stage." (PMID 35109823, 2022). "The results of the GEPIA2 and ONCOMINE database analysis also verified that the mRNA expression of DDX10 was significantly different between tumour and normal tissues." (PMID 35109823, 2022). "Analysis of the relationship between the mRNA expression of DDX10 and the staging of CRC in the ONCOMINE database indicated that DDX10 expression in tumour tissues in M1 stage or Dukes’ D stage was higher than that in tissues in M0 or Dukes’ A stage." (PMID 35109823, 2022). "As expected, compared with that in paracarcinoma tissues, the protein expression of DDX10 in tumour tissues was significantly elevated." (PMID 35109823, 2022). "The decrease in the number and total weight of metastatic tumours in mice injected with shDDX10-CRC cells also fully demonstrated that the expression of DDX10 promoted the migration of CRC." (PMID 35109823, 2022). "The mRNA and protein expression levels of DDX10 were both highly expressed in tumor tissues of CRC." (PMID 38023215, 2023). "Then, we used a lentiviral transfection method to knockdown and overexpress DDX10 to carry out cytological experiments and to construct a tumour metastasis model in mice, which helped us explore the effect of DDX10 on the growth, invasion and metastasis of CRC cells." (PMID 35109823, 2022). "Shi and Hao14 showed that silencing of DDX10 could potentially be therapeutic, and inhibit proliferation, invasion, and migration of the tumor cells, by inhibiting MAPK pathway." (PMID 32371905, 2020). "Downregulation of DDX10 not only suppressed cell growth and colony formation, inhibited migration and invasion of CRC cells in vitro, but also prevented tumor growth and lung metastasis in nude mice." (PMID 38023215, 2023).
infection (2 papers, 2025). The state of being infected such as from the introduction of a foreign agent such as serum, vaccine, antigenic substance or organism. "PCV3 Rep expression levels were significantly increased in DDX10-silenced cells than in control cells during infection (P < 0.05)." (PMID 40340395, 2025). "The protein levels of DDX10 in PCV3-infected PK-15 cells were significantly decreased at 12, 24, 36, and 48 h post-infection (hpi), which was further confirmed by an analysis of the relative densitometric ratios of DDX10 and β-actin (the corresponding internal reference) (P < 0.05)." (PMID 40340395, 2025). "Using microscopy, we confirmed the prediction of our chaperone interaction analysis, observing colocalization of DDX10, DDX18, DDX50, and GTPBP4 with VICE domains upon infection with HSV-1." (PMID 40577456, 2025). "To determine the expression of DDX10 during PCV3 infection, we analyzed the kinetics of endogenous DDX10 expression in different cell types infected with PCV3 at a multiplicity of infection (MOI) of 1 via Western blotting and quantitative real-time reverse transcription PCR." (PMID 40340395, 2025).
hematologic malignancies (1 paper, 2026). "This review provides a comprehensive analysis of DDX10, from its structural and functional features to its emerging roles in solid tumors and hematologic malignancies." (PMID 41751522, 2026).
DDX10 also shares sentences with these, for which no sentence is quoted: bladder cancer (1 paper); chondrosarcoma (1); colon cancer (1); deafness (1); foot and mouth disease (1); hearing loss (1); injury (1); lung carcinoma (1); lymphoid neoplasm (1); myeloid leukaemias (1); myeloid malignancies (1); Oral Squamous Cell Carcinoma (1); stomach cancer (1).